CD4 (CD4 molecule)
Diseases named in the same sentence as CD4 in open-access papers (continued):
Sharing a sentence is not in itself a finding about the gene and the disease.
infection (continued). "Upon infection, both WT and CD40L-/- mice show an increase in the numbers of CD4+ T cells, CD4+ CD44+ effector CD4+ CD25+ Foxp3+ Tregs compared to their respective MI." (PMID 34898656, 2021). "Consistent with this interpretation, HIV bNAbs occasionally develop within one year of infection, and at least as commonly in HIV-infected infants as adults despite the well described deficits in CD4+ T cell function that are present during early life." (PMID 34745131, 2021). "With primary infection, virus-specific CD8+ and CD4+Selplg-/- T cells accumulated to a much greater extent than wild type (WT) cells and displayed greater persistence as memory T cells due to better intrinsic survival." (PMID 34326837, 2021). "SIV infection was followed by a consistent downward trend in CD4+ and CD8+ T-cell counts during the first ten weeks after infection in both Group 1 (BCG + M. tb + SIV) and Group 2 (M. tb + SIV)." (PMID 34579182, 2021). "Using confocal microscopy, we found that CD69+CD103+CD4+ and CD69+CD103+CD8+ T cells localized to the epithelial layer surrounding large airways during infection." (PMID 34564636, 2021). "The observed shift in cell frequencies resulted in a changed CD4+/CD8+ T cell ratio in the spleen, which was significantly lower in Ifnar1-/- mice than in WT controls after PbAAma1OVA infection." (PMID 34659202, 2021). "The amounts of CD8+ and CD4+ T cells producing IL-2 in the populations of mice splenocytes were additionally analyzed by ICS on days 14 and 29 after VACV LIVP infection." (PMID 34452494, 2021). "This was also reflected in the acute fold changes of CD4+ and CD8+ T cell responses, which indicates the CD4+ T cell response is recruited early during SARS-CoV-2 infection, the CD8+ T cell response takes more time to build up with time post-infection." (PMID 34326343, 2021). "Regarding the percentage of Cyt+ CD4 T cells, in SC mice there was a significant increase to 20.5%, whereas the SIM group only showed a minor increase compared to day 3 post infection." (PMID 34925371, 2021). "We first did an in vitro experiment in which pan T cells (containing both CD4+ and CD8+ T cells), obtained from parasite-infected animals post 14 days of infection, were co-cultured with anti-CD300a antibodies treated and parasite infected BMDC." (PMID 35116028, 2021). "Whereas IFN-γ-producing CD4+ and CD8+ T cells are crucial for parasite clearance at a later stage of the infection, IFN-γ production by NK and NKT cells during the early onset is critical for efficient granuloma formation and early parasite control." (PMID 34292975, 2021). "Since the CD4 T-lymphocyte count is an important parameter of HIV disease progression, the correlation between the prevalence of infection and the number of CD4 lymphocytes was also assessed." (PMID 34959511, 2021). "A primary infection with SARS-CoV-2 provokes immune responses that generate potent anti-SARS-CoV-2 neutralising antibodies and CD4+ and CD8+ T cell responses which clear the infection and culminate with an immune response memory to fight future infection." (PMID 34804022, 2021). "In HIS-NSG mice, HTLV-1 PVL positively correlated with the frequency of Ki67+CD4+ T-cells in the spleen and MLN after 60 days of infection." (PMID 34685494, 2021). "To dissect the protective roles of TIPE proteins, we analyzed CD45+, CD4+, CD8+, IFNg- and TNFα-secreting cells in the lung at day 13 after infection." (PMID 34939151, 2021). "To map DC subpopulations in lymphoid tissues in studies of infection or vaccination we developed a panel consisting of the markers CD123, CLECL9A and CD11c in combination with CD20, Ki67 as well as CD4 and CD8." (PMID 34177929, 2021). "In fact, CD11ahi CD49dhi CD4 T cells express PD-1 and LAG-3 during infection with Plasmodium parasites." (PMID 34067904, 2021).
infection (continued). "A range of indicators, including B cells, natural killer (NK) cells, CD4 cells percentages, and anti-SFTSV IgM antibody level, were detected using the samples that were collected at the early stage of infection." (PMID 34721338, 2021). "The data demonstrated that at day 1 post infection, the SIM group showed activated multifunctional vaccine-specific CD4 T cells (IL-17+/TNFα+ Th17 or IFNγ+/TNFα+ Th1 T cells) in the GT." (PMID 34925371, 2021). "In healthy human volunteers, this approach stimulated broad, multi-potent CD4 and CD8 T cell responses that resembled those generated upon spontaneous resolution of primary infection." (PMID 34452460, 2021). "We propose an additional role for B cell-mediated trans infection, not only as an efficient means to spread HIV-1 to CD4+ T cells but as the driver in establishing the HIV-1 reservoir in TN and potential consequent control of HIV-1 disease progression." (PMID 33688006, 2021). "However, in HIV-1 controllers, CXCR5+CXCR3+PD-1low CD4+ T cells were associated with increased HIV-1 neutralizing antibody breadth and in acute HIV infection, frequencies of CXCR3+ Tfh1 cells correlated positively with p24 plasma IgG titers at 1 year post infection." (PMID 33996678, 2021). "Further experiments with isolated CD4+ and CD8+ T-cells revealed that CD8+ T-cells were both necessary and sufficient to mediate control of infection in vitro." (PMID 34122382, 2021). "Trans-infection entails first the capture of HIV virions by fibroblasts, and then their presentation to CD4+ T cells." (PMID 33976386, 2021). "Shown are the frequencies of nucleocapsid-specific CD4+ (left) and CD8+ (right) T cells, as measured by IFNγ production upon stimulation with ancestral nucleocapsid peptides, in infection-naïve (top) and convalescent (bottom) individuals." (PMID 34636722, 2021). "When analyzing this response solely within the subset of cells responding to antigen, CD4 T cells that proliferate and produce IFN-γ constitute 70% of the response at 4 weeks post-infection and 48% at 8- and 48-weeks post infection (top row)." (PMID 34336973, 2021). "Immune profiling of the lung revealed that aged mice had significant reductions both in the percentage of CD4 cells and in the CD4:CD8 ratio in the lung compared to adult controls at steady state and after infection." (PMID 34151773, 2021). "The peripheral blood count of CD4+ and CD8+ T cells in terms of absolute number and frequency display a significant reduction in patients with either moderate or severe infection." (PMID 33767626, 2021). "Briefly, as this topic will be discussed in more detail in the next section, the infection induces an increase in Mac1+, activated CD8+ and CD4+ T lymphocytes expressing CD25, CD69, and/or CD122, natural killer (NK), and NKT cells in the liver." (PMID 34578107, 2021). "In the liver, compared to mock-infected mice, the percentage of CD69+ CD4+ T-cells was significantly increased on days 4 and 8 PI indicating that CD4+ T-cells were rapidly activated following CCHFV infection." (PMID 33572859, 2021). "While on day eight post-infection, CD3+, CD3+/CD4+, CD3+/CD8+ and MAC-3+ cells decreased significantly (p ≤ 0.05) compared with their respective counterpart group on day four post-infection." (PMID 34204678, 2021). "Following infection, the MPDN-treated animals showed a reduction in the number of CD4+ T cells similar to that seen for the control group—but much less of a reduction than that seen in the other groups of treated mice." (PMID 33524030, 2021). "The 47 NCs rebounded before meeting PTC criteria, The PTC and NC groups within the ACTG cohort are matched for sex, age, ethnicity, percent treated during early infection, ART duration, and pre-ATI CD4 count." (PMID 34188039, 2021). "The incidence of infection was significantly higher in the low-level group of CD3+, CD4+ T cells, and CD4+/CD8+ T cell ratio compared with the normal level groups." (PMID 34568395, 2021).
infection (continued). "Intriguingly, a number of responding CD4+ clones, and fewer CD8+ clones, were also represented in the repertoires of both donors 1 and 2 years before the infection." (PMID 33399535, 2021). "Expanded naïve CD4 T cells were spin-infected with either AD8, MJ4, or NL4-3 at a low multiplicity of infection." (PMID 33441346, 2021). "We also detected SARS-CoV-2-specific CD4+ and CD8+ T cell responses in approximately 65% of patients 3–4 months after infection." (PMID 33563974, 2021). "SARS-CoV-2 specific CD4+ and CD8+ T cells remained detectable at the convalescent phase of infection (35 dpi) in RhMs." (PMID 34452011, 2021). "Compared with B6 mice, we found in pMT-10 mice that ESAT-61–20–specific CD4+ T cells from the lungs displayed reduced expression of CXCR3 at days 24 and 31 after infection." (PMID 34554927, 2021). "Previous studies found an expansion of CD4+ T cells producing IL-17 triggered by uncomplicated P. vivax malaria, which correlates with the number of CD4+ T cells producing IFN-γ, IL-10, and TGF-β in response to infection." (PMID 34128836, 2021). "Nevertheless, Th1 CD4+, Th1 CD8+, and Natural Killer T cells are activated to promote antiviral activity and drive the disease recovery in moderate infection." (PMID 33767626, 2021). "Greater numbers of virus-specific effector CD4+ and CD8+ T cells in Selplg-/- mice were found early after infection, and MPEC phenotype T cells with significantly elevated expression of IL-7R predominated by 8dpi." (PMID 34326837, 2021). "In our study, we observed a significant increase in the IL-17 expressing Mtb-specific CD4+ and CD8+ T cells in the high dose infection compared to the low dose at 3 weeks post-infection." (PMID 34484203, 2021). "Immunity against T. gondii requires a type I CD4+ T helper cell (TH1)-derived IFN-γ response, and in the absence of either CD4+ T cells or IFN-γ, the host rapidly succumbs to infection." (PMID 33465134, 2021). "In another study, highly functional SARS-CoV-2-specific CD4+ and CD8+ T cells were detectable for more than three months after infection." (PMID 34234787, 2021). "These CD69+ CD4+ T cells up-regulated CD44 and CD103 expression over time after infection, indicating that BALB/c mice were able to induce TRM cells in the nasal tissue after Bp infection." (PMID 33420041, 2021). "After the onset of infection, CD8+ T cells can directly kill the virus-infected cells, whereas CD4+ T cells prime both CD8+ T cells and B cells to generate an immune response." (PMID 33998837, 2021). "One to two weeks after infection, effector CD4+ and CD8+ T cells die, leaving behind antigen‐specific memory T cells that persist long after infection." (PMID 34077596, 2021). "Along with CD4+ T cells, CD8+ T cells appear to also contribute to containment of both the initial and long-term infection with Mtb." (PMID 35116036, 2021). "Infection by SARS is in part attributed to reduced numbers of T cells, primarily CD4+ T cells, leading to the host’s inability to clear the infection." (PMID 33525632, 2021). "Here, we analyze the response of CD4+ and CD8+ T cells from Trpm2-/- mice in vitro and in infection and inflammation models in vivo." (PMID 35095852, 2021). "At 5 weeks post-infection, when granuloma formation is chronic, mice were transferred with D10 RAG−/− spleen cells equivalent to 106 CD4+ cells and immunized s.c. with either CA antigen or PBS." (PMID 34943793, 2021). "Contracting (d) and expanding (e) clones include both CD4+ and CD8+ T cells and are less abundant in pre-infection repertoires." (PMID 33399535, 2021). "The i.v. or oral infection with Listeria monocyotgenes produced an Ag-specific memory CD4 T cell population that produced IFN-γ upon restimulation, whereas intranasal infection promoted IL-17–producing memory CD4 T cells." (PMID 34103371, 2021).
infection (continued). "Our results confirm that the frequency of CD4+ and CD8+ T cells producing IL-2 drops along with the acute illness, but a peak of IL-2 production on day four after infection preceded the decay." (PMID 34869064, 2021). "For HSV-2, CD4+ and CD8+ TRMs are established after initial infection and then play a key role in controlling subsequent recurrences." (PMID 33668777, 2021). "After the challenge infection with 10 LD50 of the avian influenza virus, the highest CD4+ and CD8+ T cell populations were observed from the lungs of HANA-VLP-immunized mice." (PMID 34684240, 2021). "In vivo, sites of HSV-2 reactivation are surrounded by CD4+ and CD8+ tissue resident T cells and other immune cells which quickly respond to infection and prevent widespread cell death." (PMID 35126336, 2021). "As intraepithelial CD4+ T lymphocytes occur at low abundance, and target cells expressing CD4 and CCR5 are more likely to populate the basal epithelium and underlying lamina propria, epithelial cells as ‘transient’ reservoirs could enhance the probability of acquiring infection." (PMID 33816339, 2021). "The enduring LIP process due to the presence of infections could lead to accumulation of cells with the following characteristics: loss of diversity of the TCR repertoire, increase in number of exhausted CD28− T cells, and functional changes in CD4+ T cell subsets." (PMID 33923792, 2021). "Ninety percent of the CD4 and 60–70% of the CD8 brain T cells showed a CD44+KRLG1- memory phenotype during the early and late stages of infection." (PMID 34587172, 2021). "The percentage of CD4+GATA3+IL-4+ Th2 cells and CD4+CXCR5+ Tfh cells, and IL-4 production in the 8-week-old mice significantly increased on day 5 and day 10 after P. yoelii 17XNL infection." (PMID 33430765, 2021). "Our findings demonstrated that significant numbers of antigen-specific IL-17-producing CD4 TRM cells and Siglec-F+ neutrophils accumulate in the nasal tissue during primary infection of mice with B. pertussis." (PMID 33976385, 2021). "Further, the absolute counts of CD3+CD4+, CD3+CD8+, and CD19+ were decreased in the spleen of mice after MP4 infection." (PMID 34566960, 2021). "In mice, CD4+ T cell depletion enhanced CD8+ T cell breadth and function in response to infection with murine gamma herpesvirus." (PMID 34745131, 2021). "The frequency of Tregs (CD4+CD25+FOXP3+) and activated T CD127+ cells (CD4+CD25+FOXP3−CD127hi) in infected mice was determined at different times post-infection in the peritoneum and in important secondary lymphoid organs like lymph nodes and spleen." (PMID 33928043, 2021). "CD4+ T-cells can promote effective B-cell and CD8+ T-cell responses through licensing of APCs, recruitment of CD8+ T-cells to the sites of infection, and direct interaction with these cell types." (PMID 33572859, 2021). "In AV-infected animals, a robust CD4+ and CD8+ T-cell response, involving induction and proliferation of cytotoxic T cells, was induced in blood and SLOs by the second week after infection." (PMID 33398113, 2021). "Although HIV-1 induction of apoptosis in bystander CD4+ T cells was reported to be driven by Env glycoproteins, gp120 and gp41, Env-mediated autophagy during HIV-1 early infection was first described in 2006." (PMID 33995324, 2021). "Whilst treating, the decrease of CD235a+, CD4+, CD8+, and CD19+ EVs demonstrated their values in pathogenesis of the infection or ability to additionally concretize treatment effectiveness." (PMID 33925492, 2021). "Prior work from our group demonstrated that one mechanism by which mucosal stromal fibroblasts enhance HIV infection of CD4+ T cells was through trans-infection, as defined by the ability of HIV-pulsed fibroblasts to transfer infectious virus to CD4+ T cells." (PMID 33976386, 2021). "Accordingly, basophils, reduced in severe patients with ongoing infection, were increasingly restored in the R1-R2 time points, along with a recovery of CD8+ and CD4+ T cells and B cell populations." (PMID 34745145, 2021).
infection (continued). "The expression of “exhaustion markers” on CD4+ cells, together with the presence of Tregs and anti-inflammatory cytokine production, are long lasting effects in children even after cure, which may contribute to a prolonged state of immunosuppression until the next infection." (PMID 34684226, 2021). "Seminal studies have shown that subepithelial CD4+ T cells and DCs expressing surface receptors DC-SIGN or Siglec-1 are key actors in the early establishment of HIV-1 entry and infection in human tissues." (PMID 33637808, 2021). "CD32+CD4+ T cells were increased in both SLT and gut during SIVmac infection, but only in gut during chronic SIVagm infection." (PMID 34220857, 2021). "In accordance with the FDS data, we observed a substantially lower proportion of cytokine-expressing KLRG1+ CD4 T cells after MPT70 stimulation compared to ESAT-6, and this difference was sustained throughout the infection." (PMID 33879592, 2021). "The effector CD4 cells represented by CD62L−HLA-DR− and the memory CD4 cells represented by CD45RO+ were prominently upregulated relative to HCs, as expected in the course of infection." (PMID 33808906, 2021). "α4β7+ CD4+ T lymphocyte subset thus plays a crucial role in mucosal transmission and we report for the first time that CD4+ T cells expressing both β7 and CCR5 were conducive to trans-infection following co-culture with HIV-1 exposed vaginal epithelial cells." (PMID 33816339, 2021). "The percentage of all T lymphocytes (CD5+), as well as of CD4+ Thelper cells and CD8+ Tcytotoxic cells, decreases after infection with HA- strains, but increase slightly after infection with HA+, starting 4–8 h p.i.." (PMID 33805607, 2021). "HTLV-1 infection triggered the differentiation of both naïve CD4+ and CD8+ T-cells, particularly into effector memory cells, as observed in the blood, spleen, and MLN after 30 and 60 days of infection when compared to controls." (PMID 34685494, 2021). "A subset of primed CD4+ and CD8+ T cells differentiates into long-acting memory cells after the infection subsides." (PMID 33335518, 2020). "PP-SLIDE revealed, as expected, that PRE cells had a higher CD4 MSI than the total population of uninfected T cells, suggesting that HIV selects cells expressing high levels of CD4 for infection." (PMID 32452381, 2020). "CD4+ and CD8+ T cells are activated through similar mechanisms, but they play unique functional roles in infection." (PMID 32974217, 2020). "WT B6 mice were infected with LCMV clone 13, and ALCAM expression on CD4+ and CD8+ T cells was analyzed during the acute (day 8) and chronic (day 30) phase of the infection and compared to naïve mice (day 0)." (PMID 33375121, 2020). "CD4+ and CD8+ T cell responses and a robust antibody response including IgM, IgA, and IgE antibodies develop by 2 weeks post infection, suggesting an essential role for T cells, mucosal antibodies, and/or extracellular antibody effector functions." (PMID 33384972, 2020). "We first infected the activated primary CD4 T cells with single-round CXCR4-tropic HIV-1 pseudoviruses, sorted GFP+ and GFP− cells 4 days post infection, and then conducted RT-qPCR in these two groups of cells." (PMID 33270809, 2020). "In order to evaluate subpopulations of CD4+ T lymphocytes in the course of CBM, total lymphocytes were isolated from dLN (popliteal) and infection site (footpad), followed by the analysis of T helper phenotypes." (PMID 32542003, 2020). "Our data demonstrate that CMTB leads to a profound and early influx of both CD4+ and CD8+ T cells after aerosol infection, which likely contributes to the protective effect and the long-term maintenance of protective immunity." (PMID 32673357, 2020). "The aim of our study was to evaluate the CD4+ and CD8+ responses to influenza A and B infection in a cohort of SOT patients." (PMID 32572168, 2020). "This individual had SARS-CoV-2-specific CD4+ and CD8+ T cells, suggestive of an ability of T cell-mediated immunity to control infection." (PMID 33010815, 2020).